TGFB1 (transforming growth factor beta 1)
Diseases named in the same sentence as TGFB1 in open-access papers (continued):
Sharing a sentence is not in itself a finding about the gene and the disease.
ovarian carcinoma (continued). "Expression of TGFβ1, melanoma antigen (MAGE) 3, and 6 is upregulated in ovarian cancer derived-exosomes compared with that in exosomes derived from benign ovarian lesions (serous cysts) or normal cells suggesting that these proteins could be biomarkers to distinguish malignant and benign tumors." (PMID 38796525, 2024). "In addition, as the binding partner of ITGB6, ITGAV, had no independent effect on activating latent TGFβ1 in 3D-cultured ovarian cancer spheroids." (PMID 34621667, 2021). "Such as, TGFβ1 could induce EMT and metastasis of human ovarian cancer cells." (PMID 30250403, 2018). "In addition, TGFβ1 could also upregulate the expression of SMYD3 and ITGB6 in return to form a positive feedback loop with the SMYD3/ITGB6/TGFβ1 pathway to enhance the metastasis of ovarian cancer spheroids." (PMID 34621667, 2021). "As downstream targets of the TGFβ1/SMAD3 pathway and essential participants in EMT promotion, N-cadherin, Vimentin, E-cadherin and Snail were found to be regulated by SMYD3 and ITGB6 and could contribute to enhanced invasion and adhesion in ovarian cancer spheroids." (PMID 34621667, 2021). "Although BOTs are not entirely recognized as malignant tumors and are not seen as a necessary process of transformation into ovarian cancer, in this study, we found some biomarkers related to EMTs, such as IL6, AKT1, MAPK3, SRC, TWIST1, and TGFB1." (PMID 33921111, 2021). "TGFB1 does not induce SNAI1 expression in OVSAHO or OVCAR8; for this reason, ovarian cancer cell lines were treated with EGF." (PMID 33806868, 2021). "Of note, we observed how in ovarian cancer cells the secretion of TGF-β1 protein, but not the transcription of the TGFB1 gene (not shown), was reduced by RSK1/RSK2 silencing." (PMID 26625210, 2016). "TGFB1 and TGFBR1 expression did not affect survival (data not shown), while TGFB2, TGFB3, TGFBR2, and TGBR3 overexpression decreased patient survival among ovarian cancer patients when the microarray data was assessed." (PMID 38196068, 2024).
colon carcinoma (523 papers, 1999 to 2026). "Induction of the protooncogene c-fos by TGFβ1 in poorly invasive HD3 colon carcinoma cells was associated with induction of some growth-inhibitory signals, while this signal transduction pathway is suppressed in TGFβ1-stimulated invasive colon carcinoma U940." (PMID 32393769, 2020). "A few years ago, it was shown that, upon RSV treatment, miR-663 was upregulated both in human THP-1 monocytes, where it targets transcripts encoding pro-inflammatory JunB and JunD, and in human SW480 colon cancer cells, where it targets TGFβ1 transcripts." (PMID 29987196, 2018). "Interestingly, while the wound gap was more rapidly closed in TGFβ1-treated colon cancer cells, the gap area closure caused by treatment with TGFβ1 was inhibited by NCKAP1 knockdown." (PMID 36639705, 2023). "Specifically, these shared pathways with IBD were linked to inflammation (TNF, IL-1A, IL-1B, NFkB, IL-6) and growth (TREM1, TGFB1), while other pathways shared with colon cancer were associated with colorectal metastatic signaling, growth (TREM1, NFkB and HMGB1) and inflammation (IL-8, IL-6)." (PMID 35323693, 2022). "This study elucidates the mechanism by which curcumol inhibits angiogenesis and metastasis in colon cancer via the OTUB1/TGFB1 pathway." (PMID 40430059, 2025). "Researchers also noticed that the use of resveratrol in the treatment of colon cancer cells led to a reduction in TGFβ1 and its downstream effector SMAD3, as explained by the action of miR-663 on TGFβ1 transcripts." (PMID 37373289, 2023). "TGFβ1-treated colon cancer cells underwent morphological changes, including adopting a mesenchymal shape, but NCKAP1 knockdown cells did not change to a mesenchymal morphology after treatment with TGFβ1." (PMID 36639705, 2023). "These genes encode the extracellular matrix proteins LAMA3 and LAMC2, which have been detected in invasive colon cancer cells and are regulated by transforming growth factor beta 1 and the hepatocyte growth factor produced in the tumor microenvironment." (PMID 36077674, 2022). "It has been shown that higher relative levels of TGFB1 gene expression are observed more frequently in patients with colon cancer accompanied by lymphocytic infiltration." (PMID 35798776, 2022). "For instance, constitutively repressing endogenous TGFβ1 expression and aTGFβ activity in human colon carcinoma cells retained their functional receptor complexes and the ability to respond to exogenous TGFβ but led to a more progressed phenotype." (PMID 33802809, 2021). "Our study implied that TGFβ1 greatly participated in the modulation of the colon cancer TIME through communicating with T cells CD4 naïve and Tregs." (PMID 33995472, 2021). "MALAT1 is also increased in colon cancer cells, directly binding to miR-663a, thus acting as a competing endogenous lncRNA; as a result, important cancer-related miR-663a targets (TGFB1, PIK3CD, P21, JunB, and JunD) were affected." (PMID 32183400, 2020). "For instance, Geng and co-workers evidenced that TGFβ1 decreased VEGFA expression via Smad3P activation in colon cancer cells." (PMID 31632347, 2019). "This agrees with our previous studies in murine colon carcinomas that showed increased levels of TGFβ1 in the medium of TG2 transfected clones, which was inhibited by the inclusion of site-directed TG2 inhibitors in the culture medium." (PMID 28223538, 2017). "In both the Tgfb1−/−Rag2−/− and Smad3−/− models, colon cancer develops only in conjunction with the presence of gut microbial Helicobacter species." (PMID 28951889, 2017). "Our previous work using the CT26 mouse CRC cells indicated the relationship between TG2 expression, TGFβ1 and FN deposition in colon cancer." (PMID 28223538, 2017). "Taken together, these results suggest that lithium reduces the expression of TGFBIp in colon cancer cells by inhibiting the TGFβ1-Smad3 signaling pathway via GSK3ββ inactivation." (PMID 26857144, 2016).
colon carcinoma (continued). "A recent study has reported that genetic variants in the TGFB1 pathway related genes (MAPK1, RUNX1 and RUNX2) are associated with CIMP-high colon cancer." (PMID 21949851, 2011). "Of note, these authors demonstrated that TGFβ-1-mediated EMT directly drives vimentin production in colon cancer cells." (PMID 21747928, 2011). "Elevated expression of PRNP in homozygous mice was accompanied by increased expression of a set of genes that we previously identified as PrPC gene targets in colon cancer cells, namely App, Bace1, Dkk3, Pdgfc and Tgfb1, thus validating our model as a robust PRNP-overexpressing paradigm." (PMID 38589873, 2024). "Furthermore, TGFβ1 enhances the dissemination of colon carcinoma cells to the liver through attachment to CAFs." (PMID 36936987, 2023). "The inhibition of ALBU and HNF4 expression, as well as the observed morphological changes associated with the modulation of Vimentin and CK8/18, can be ascribed to TGFβ1 activity, which is known to be carried by EVs, including those released by colon cancer cells." (PMID 37072829, 2023). "When FJX1 was knocked down in colon cancer cells, the expression of TGFB1 and IL-10 also decreased, suggesting that FJX1 may affect the polarization of macrophages and thus the tumor microenvironment." (PMID 37324001, 2023). "Furthermore, the increase in FN induced by TGFβ1 was decreased in NCKAP1 knockdown colon cancer cells." (PMID 36639705, 2023). "CTNNB1 expression was recovered by siNCKAP1 in TGFβ1-treated colon cancer cells." (PMID 36639705, 2023). "A study on the colon cancer patients has identified the negative association of GG genotype of TGFβ-1 +29 C/T with cancer which is suggestive of its protective impact against the disease." (PMID 36215278, 2022). "However, in CT26 colon cancer, there is a relatively greater expression of TGFβ1 than TGFβ3 by comparison of MFI values." (PMID 34789823, 2021). "Paired analysis and GSEA were carried out to understand the role of TGFβ1 in colon cancer." (PMID 33995472, 2021). "Curiously, FN1 and TGFB1 are upregulated by 5-fluorouracil in colon carcinoma cells." (PMID 32824266, 2020). "The use of resveratrol in the treatment of colon cancer cells has led to a reduction in TGFβ1 and its downstream effector SMAD3, this could be explained by the target of miR-663 on TGFβ1 transcripts." (PMID 30202241, 2018). "Additionally, knockdown of c-Fos suppresses the migratory behavior of human colon carcinoma cells by blockade of TGFβ1 production in athymic mice." (PMID 27602752, 2016). "These include a reduction in ERK signaling, diminished TGFβ1 production, decreased expression of the plasma membrane-cytoskeletal linker Ezrin, as well as attenuation of the paracrine effects of colon carcinoma-secreted factors on fibroblast migration and mitogenesis." (PMID 23755307, 2013). "In the mouse, a deficiency of TGFβ1 combined with an absence of T-cells (Tgfb1-/-; Rag2-/-) results in a high occurrence of colon cancer." (PMID 17615082, 2007). "Finally, not only does TGFβ1 contribute to the development of Tregs, but Tregs themselves suppress T cell function through TGFβ1, and blockade of TGFβ1 signaling in CD8+ T cells has been shown to prevent Treg-mediated suppression of anti-tumor immunity in a murine colon carcinoma model." (PMID 27589814, 2016). "Our study confirmed that OTUB1 overexpression upregulates TGFB1 and VEGF expression, enhancing the proliferative, migratory, and invasive capacities of human colon cancer cells (HT-29 and Caco-2), as well as the tubule formation ability of HUVECs." (PMID 40430059, 2025). "Mechanistic studies revealed that curcumol downregulates OTUB1, TGFB1, and VEGF expression in both colon cancer and vascular endothelial cells." (PMID 40430059, 2025).
colon carcinoma (continued). "Curcumol treatment counteracted these effects by suppressing TGFB1 and VEGF expression following OTUB1 overexpression, reducing colon cancer cell proliferation, migration, and invasion and inhibiting HUVEC tubule formation." (PMID 40430059, 2025). "In contrast, in two papillary thyroid carcinoma cell lines, miR-663 behaved as a tumor-suppressor by targeting TGFβ1, thus inhibiting epithelium-to-mesenchyme transition, similar to what was previously found in SW480 colon cancer cells." (PMID 29987196, 2018). "Colon cancer and adjacent normal sections were stained for SMAD4, TGFβ1, and CD11b, a myeloid lineage marker expressed by tumor-associated macrophages, neutrophils, and other inflammatory cells (N = 19)." (PMID 27270652, 2017). "For example, in colon cancer cells, growth suppression by TGFβ1 was dependent on actA, while cellular migration was not." (PMID 36717814, 2023). "Additionally, EVs purified from MC38 colon carcinoma cells overexpressing IL-12 and deprived of TGF-β1 by transfecting shRNA molecules targeting TGFB1, efficiently inhibited tumor growth and induced anti-tumor immunity, together with DC-based vaccines." (PMID 35493080, 2022). "Consistent with the results of DSS-induced colitis, the expression of Tgfb1-3 was not elevated in the colon in AOM/DSS-treated mice and ApcMin/+ mice, and anti-TGFβ antibody did not reduce the expression of Il11 in colon tumor tissues in these mice." (PMID 33863879, 2021). "The TMA immunofluorescence data of three selected candidate biomarkers, β-catenin, TGFβ1 and NFκB verified that they are highly overexpressed in colon cancer stem cells and negative in bulk cancer cells." (PMID 28503055, 2016). "Bates and Mercurio demonstrated that TGFβ1-induced EMT is accelerated dramatically by the presence of activated macrophages, identified TNF as the critical factor produced by macrophages that accelerates the EMT in a model of colon cancer." (PMID 20047688, 2010). "GO enrichment analysis showed that specific proteins, including TGFβ1, adenomatous polyposis coli (APC), CTNB1, low-density lipoprotein receptor-related protein (LRP) 5 (LRP5), LRP6, JAK1, ST14, and TP53BP1, were hypothetical CD151-interacting proteins in colon cancer." (PMID 33767593, 2021). "αvβ6, originally identified on airway epithelial cells, and as a fibronectin receptor on colon carcinoma cells, was shown in a landmark study to be a local activator of latent TGFβ, and lack of αvβ6 in mice startlingly phenocopied the TGFβ1 knock-out mouse (see Introduction)." (PMID 28832494, 2017). "Epithelial character was weakened in TGFβ1-treated colon cancer cells, but their epithelial properties did not disappear in the NCKAP1 knockdown state even when they were treated with TGFβ1." (PMID 36639705, 2023).
glioblastoma (450 papers, 2009 to 2026). The most malignant astrocytic tumor (WHO grade IV). "CrkL expression was detected in U87 and U251 glioblastoma cell lines, and CrkL was activated by transforming growth factor-beta 1 (TGF-β1)." (PMID 40362257, 2025). "Taken together, our findings suggest a synergistic effect in glioblastoma in which regulatory T cells activate TGFB1 signaling, leading to EMT, which is enhanced by RAS activation." (PMID 38981682, 2024). "More recently, THBS1 was recognized as a central regulator of glioblastoma invasiveness, as a bioinformatics analysis predicted its high connectivity with collagens, TGFβ1, and integrins." (PMID 39304722, 2024). "TGFβ1 induces THBS1 (thrombospondin-1) expression via Smad3, which contributes to invasive behavior during glioblastoma expansion; TGF-β also stimulates both THBS1 and CISP/THBS2 synthesis by bovine adrenocortical cells." (PMID 36535930, 2022). "Among them, IDO1, PDCD1, and TGFB1 are promising immune-modulatory targets that are in the focus of current clinical research in glioblastoma." (PMID 35734424, 2022). "Here, MSC were found capable of stimulating human Glioblastoma (GBM) cell proliferation through a paracrine effect mediated by TGFB1." (PMID 29872504, 2018). "Regulation of MET expression by TGFβ1 seems to be tumor‐type‐specific as in glioblastoma, TGFβ suppresses HGF/MET pathway activity." (PMID 30004628, 2018). "Integrative bioinformatic analysis confirmed the reciprocal crosstalk between tumour and microenvironment and suggested a key role for TGFβ1 and extracellular matrix proteins as major interaction modules that shape glioblastoma progression." (PMID 27049916, 2016). "MMP-2 also facilitates cancer cell invasion in glioblastoma multiforme, a brain tumour in which TGFβ1 is highly expressed." (PMID 26867675, 2016). "Following brain injury, microglia and astrocytes produce large concentrations of TGFβ1, whilst glioblastoma multiforme enhances TGFβ1 expression, possibly due to the increased and abnormal angiogenesis." (PMID 26867675, 2016). "Although TGFβ1 has been shown to inhibit astrocyte proliferation, it has been shown to increase the proliferation of glioblastoma." (PMID 20221422, 2010). "In addition, B2M signaling in glioblastoma cells activates the PI3K/AKT/MYC/TGFβ1 axis, which sustains cancer stem cell properties and promotes M2-like macrophage polarization." (PMID 40842996, 2025). "On the contrary, changes in the expression of TGFB1 have been widely described in glioblastoma." (PMID 38794149, 2024). "In primary glioblastoma cases, M1 macrophages were classified by CIBERSORT as monocyte-derived tumor-associated macrophages (Mo-TAMs), based on the expression of genes such as TGFB1, CLEC12A, and FXYD5." (PMID 35203505, 2022). "Similarly, transcripts encoding TGFbeta isoforms (TGFB 1, 2, 3) were upregulated in glioblastomas compared to control brain tissues as was also reported in previous studies." (PMID 33494271, 2021). "Moreover, the transforming growth factor beta 1/SMAD family member 3 (TGFB1/SMAD3) plays a key role in the extracellular matrix (ECM) production which can lead to glioblastoma aggression." (PMID 27716259, 2016). "Using the Glioblastoma Bio Discovery Portal (GBM-BioDP), an online resource for accessing and displaying interactive views of the TCGA GBM data set, we visualized the expression levels of TGFβ1/3 and TβRII in the four GBM subtypes." (PMID 32944398, 2020). "Using human glioblastoma cell cultures, Seung-Hoon Lee and Myung-Shin Lee at Eulji University School of Medicine, Daejeon, South Korea, and co-workers demonstrated how the interaction between NgR and another protein enhances TGFβ1 pathway activity and prevents NgR maturing." (PMID 31649250, 2019). "The functional matrix highlighted multifunctional hubs such as STAT3, TGFB1, and PRMT5, bridging several biological processes central to glioblastoma pathogenesis." (PMID 41179304, 2025).
glioblastoma (continued). "Hence, our analysis suggests that a combined therapy targeting RAS and TGFB1 or their downstream targets could have a synergistic therapeutic effect for glioblastoma, again demonstrating the potential of SiPSiC analysis to accelerate the development of targeted therapy." (PMID 38981682, 2024). "Bioinformatics analysis and Western blotting showed that SECTM1 regulates glioblastoma invasion and EMT-like processes mainly through the TGFβ1/Smad signaling pathway." (PMID 38164182, 2024). "FAP expression correlated with TGFB1 and TGFB3, but not TGFB2 in all glioblastomas and in the mesenchymal subtype." (PMID 33494271, 2021). "To further confirm this, we detected the PAI-1 and Smad 7 mRNA level in glioblastoma cells treated with TGF-β1, the data showed that PAI-1 mRNA was increased significantly in four cells treated with TGFb1 for 48 h, however Smad7 mRNA was not enhanced as highly and significantly as PAI-1 mRNA." (PMID 28912531, 2017).